GHRH (growth hormone releasing hormone)
Diseases named in the same sentence as GHRH in open-access papers (continued):
Sharing a sentence is not in itself a finding about the gene and the disease.
type 2 diabetes (4 papers, 2016 to 2024). "Thus, understanding and targeting GHRH signaling could provide therapeutic avenues for managing type 2 diabetes and associated comorbidities." (PMID 39560873, 2024). "We then focus on the role of GHRH in type 1 and type 2 diabetes, as well as metabolic diseases." (PMID 39560873, 2024). "Therefore, if GLP-1 signaling is impaired, which can occur in both type 1 and type 2 diabetes, GHRH could serve as a potential alternative treatment option." (PMID 39560873, 2024). "Tesamorelin, the only GHRH agonist used in clinical practice to date, has been shown to reduce serum total cholesterol and non-HDL cholesterol levels in individuals with type 2 diabetes." (PMID 39560873, 2024).
acute myeloid leukemia (3 papers, 2023 to 2025). Acute myeloid leukemia (AML) is a group of neoplasms arising from precursor cells committed to the myeloid cell-line differentiation. "However, the potential of the GHRH antagonist MIA-602 in addressing the resistance of acute promyelocytic leukemia (APL), as well as its ability to produce synergistic effects in acute myeloid leukemia (AML), have not yet been studied." (PMID 37370714, 2023).
carcinoid syndrome (3 papers, 2022 to 2025). "Twenty-three (54.8%) cases were functional tumors, including carcinoid syndrome, but there were also rare ones secreting glucagon, growth hormone-releasing hormone (GHRH), and PTH-related protein (PTHrP)." (PMID 35207193, 2022).
epilepsy (3 papers, 2017 to 2024). A brain disorder characterized by episodes of abnormally increased neuronal discharge resulting in transient episodes of sensory or motor neurological dysfunction, or psychic dysfunction. "If ITT is contraindicated (for example due to epilepsy or ischaemic heart disease), assessment can be done with either arginine, glucagon, levodopa, growth hormone-releasing hormone (GHRH) or clonidine stimulation test." (PMID 39839805, 2024). "First, we performed Western blotting to investigate GHRH expression levels in the cortices of patients with epilepsy (n = 22) and controls (n = 12); GAPDH expression was assessed as an internal loading control and was present as a 36 kDa band." (PMID 29273763, 2017). "In the KA-induced epilepsy mouse model, the GHRH expression levels in the hippocampus and cortex of epileptic mice were 1.17 ± 0.11 and 1.44 ± 0.08 compared to 0.85 ± 0.09 and 0.75 ± 0.11 in the control mice, respectively." (PMID 29273763, 2017). "Does GHRH enhance the inhibitory effect of GABA to prevent epilepsy by increasing the GABA level and activating GABARs?" (PMID 29273763, 2017). "Next, we examined GHRH expression in mouse models of epilepsy induced by KA and PTZ using Western blotting." (PMID 29273763, 2017). "Further studies are needed to test whether GHRH directly interacts with GABAARs to further activate them, thereby enhancing the inhibitory effect to prevent epilepsy." (PMID 29273763, 2017). "Western blots were used to observe the differences in GHRH expression between the normal group and the epilepsy group, immunofluorescence was performed to explore the localization of GHRH in the brain, and coimmunoprecipitation was used to observe the interaction between GHRH and GABARs." (PMID 29273763, 2017). "The primary finding of this study is that GHRH expression was significantly increased in the brains of both patients with TLE and in two mouse models of epilepsy induced by either KA or PTZ." (PMID 29273763, 2017). "In this study, GHRH expression was first assessed by Western blotting and was significantly increased both in patients with TLE and in two mouse models of epilepsy induced by either KA or PTZ." (PMID 29273763, 2017). "Does GHRH increase GABA levels and activate GABARs to protect against epilepsy?" (PMID 29273763, 2017).
hypothalamic tumors (3 papers, 2012 to 2026). "Other causes, such as increased growth hormone-releasing hormone production from hypothalamic tumors, ectopic growth hormone-releasing hormone production, and ectopic GH secretion from nonendocrine tumors, are rare." (PMID 23008710, 2012).
ischemic stroke (3 papers, 2018 to 2026). A stroke disorder caused by obstruction of blood flow to the brain, due to thrombotic (local blood clot formation) or embolic (due to a blood clot or other material traveling from another site) event. "Beyond its role in promoting pituitary growth hormone (GH) secretion, growth hormone-releasing hormone (GHRH) has shown neuroprotective effects in experimental ischemic stroke and spinal muscular atrophy." (PMID 41946684, 2026). "The articles included were identified through systematic searches in PubMed using keywords such as "GHRH analogues", "cardiovascular disease', and "ischemic stroke", with selection based on relevance to therapeutic applications and preclinical efficacy." (PMID 42292828, 2026).
lung NETs (3 papers, 2021 to 2024). "Plasma GHRH levels were elevated [38,088 ng/l; RR, <250–300], and a diagnosis of ectopic acromegaly secondary to lung neuroendocrine tumor was considered." (PMID 39449742, 2024).
mood disorder (3 papers, 2020 to 2025). A cognitive disorder a disturbance in which the person's mood is hypothesized to be the main underlying feature. "Further investigations are needed to confirm a role for GHRH analogs in mood disorders." (PMID 31959947, 2020). "We aimed to further investigate the effects of a novel GHRH antagonist of the Miami (MIA) series, MIA-602, on emotional disorders and explore the relationships between the endocrine system and mood disorders." (PMID 37998350, 2023).
non-small cell lung carcinoma (3 papers, 2008 to 2022). A group of at least three distinct histological types of lung cancer, including non-small cell squamous cell carcinoma, adenocarcinoma, and large cell carcinoma. "Interestingly, the silencing of p21 expression in human non-small cell lung carcinoma (NSCLCs) cells abolished the antiproliferative effect of GHRH antagonist JMR-132." (PMID 36232554, 2022). "In addition, it was revealed that GHRH antagonists MZ-J-7-138 or JV-1-92, in combination with docetaxel, reduced the ERK upstream protein K-RAS and COX-2 in mice xenografted with non-small cell lung cancer cells (NSCLCs)." (PMID 36232554, 2022).
small cell lung carcinoma (3 papers, 2008 to 2025). Small cell lung cancer (SCLC) is a highly aggressive malignant neoplasm, accounting for 10-15% of lung cancer cases, characterized byrapid growth, and early metastasis. "Growth hormone-releasing hormone antagonists suppress the in vivo growth of various experimental cancers such as prostatic, mammary, ovarian, renal cell carcinomas, small cell lung carcinomas, pancreatic and colorectal carcinomas, endometrial, osteogenic sarcomas as well as malignant glioblastomas." (PMID 18506184, 2008).
ACTHomas (2 papers, 2021 to 2023). "Noteworthy, this is also the first demonstration of the inhibitory activities of GHRH antagonists in corticotroph adenoma cells." (PMID 34439107, 2021).
anaemia (2 papers, 2009 to 2025). "Hematological parameters were also significantly improved in the GHRH-treated dogs, reversing the cancer-associated anemia." (PMID 19149896, 2009). "Our previous studies supported the hypothesis that an increase in GHRH will positively impact renal function, anemia, and immune dysfunction, as well as reverse wasting, and extend life expectancy of chronically ill patients." (PMID 19149896, 2009). "Iron deficiency is often seen in CRF and is a common cause of anemia; therefore treatment with GHRH may increase iron levels without the adverse effects of parenteral iron therapy." (PMID 19149896, 2009). "Administration of GHRH to CRF patients may improve their quality of life by acting as an immune-enhancing agent and treating their anemia." (PMID 19149896, 2009).
cerebrovascular disease (2 papers, 2022 to 2026). "When contraindicated (patients with seizures and cardio/cerebrovascular disease), alternative tests such as the glucagon, the macimorelin, and the GHRH plus arginine/GH secretagogue tests can be used, which are well described elsewhere, although there is a lack of normative data at transition." (PMID 35262704, 2022).
childhood cancer (2 papers, 2019 to 2021). "In the presence of an underlying hypothalamic derangement, the GHRH + ariginine test is the one with the highest false negative rate, as observed in childhood cancer survivor patients." (PMID 34267285, 2021). "Testing with ITT, GHRH (with or without arginine), and glucagon has been recommended, in this order, for the diagnosis of GHD in adult survivors of childhood cancer, while no recommendations were provided for the diagnosis of GHD after adult height achievement in COGHD." (PMID 31417499, 2019).
chronic kidney disease (2 papers, 2009 to 2025). Impairment of the renal function secondary to chronic kidney damage persisting for three or more months. "Growth hormone-releasing hormone (GHRH) plasmid-based therapy for the treatment of chronic renal failure and its complications was examined." (PMID 19149896, 2009). "Chronic renal failure (CRF) can affect the growth hormone releasing hormone/growth hormone/insulin-like growth factor-I (GHRH/GH/IGF-I) axis which can lead to growth retardation in children and is associated with increased morbidity and mortality." (PMID 19149896, 2009).
gastric cancer (2 papers, 2018 to 2024). A primary or metastatic malignant neoplasm involving the stomach. "The inhibition of tumor growth which accompanied the treatment of NCI-N87 stomach cancer and other tumors by the GHRH agonists in vivo is the subject of our intense investigations, which will be reported elsewhere." (PMID 29983893, 2018). "Thus, the anti-neoplastic effect of GHRH antagonist, MIA-602, was found to be associated with blockage of GHRH-R-mediated PAK1/STAT3/NF-κB pathways in gastric cancers." (PMID 29983893, 2018). "Another GHRH agonist, MR-356, lowered serum IGF-l and inhibited tumor growth in nude mice bearing xenografted NCI-N87 human stomach cancers." (PMID 29983893, 2018).
Glucose intolerance (2 papers, 2024 to 2025). Glucose intolerance (GI) can be defined as dysglycemia that comprises both prediabetes and diabetes. "Knockdown of CaSR in adult mice specifically in the hypothalamic arcuate nucleus, where GHRH, POMC and AgRP neurons reside, also resulted in increased body weight, adiposity, leptin resistance, and glucose intolerance, and reduced bone mass." (PMID 40501942, 2025).
lung adenocarcinoma (2 papers, 2025). A carcinoma that arises from the lung and is characterized by the presence of malignant glandular epithelial cells. "The potential radiosensitizing effects of GHRH antagonists were evaluated in primary NSCLC cells derived from human lung adenocarcinoma tumors." (PMID 40244089, 2025).
lymphoma (2 papers, 2024 to 2025). A malignant (clonal) proliferation of B- lymphocytes or T- lymphocytes which involves the lymph nodes, bone marrow and/or extranodal sites. "GHRH peptide was also localized to immune cells, such as monocytes, T cells, and B cells leading to the first attempt of using GHRH-R antagonism as a means of treating lymphoma." (PMID 39417961, 2024).
lymphopenia (2 papers, 2018). Reduction in the number of lymphocytes. "We have previously shown that mice with generalized ablation of growth hormone (GH) releasing hormone (GHRH) gene (Ghrh−/−) have normal thymus and T-cell development, but present a marked spleen atrophy and B-cell lymphopenia." (PMID 30333823, 2018).
MEN1 syndrome (2 papers, 2021 to 2026). "MEN1 syndrome-related childhood-onset GH-secreting adenoma or GHRH-secreting tumours are rare but described." (PMID 33805450, 2021).
pituitary disease (2 papers, 2006 to 2023). "Our results, based on a considerable group of patients with a history of hypothalamic–pituitary disease, suggest that, with this new approach, the GHRH + ARG cut-offs should be revised." (PMID 37062055, 2023). "Although the GHRH-arginine stimulation test is a valid measure of GH secretion in patients with pituitary disease, and does discriminate between GH-deficient and GH-sufficient individuals, the test does not necessarily reflect physiological GH secretion in subjects without pituitary disease." (PMID 16886956, 2006).
pleural mesothelioma (2 papers, 2022 to 2025). A neoplasm that arises from the mesothelial cells of the pleura. "Thus, these novel results suggest that GHRH antagonists could improve the anticancer effectiveness of standard therapy in pleural mesothelioma." (PMID 36232554, 2022).
pneumonia (2 papers, 2013 to 2014). An acute, acute and chronic, or chronic inflammation focally or diffusely affecting the lung parenchyma, caused by an infection in one or both of the lungs (by bacteria, viruses, fungi, or mycoplasma.). "GHRH agonists could improve lung function in pathologies associated with pulmonary permeability edema, such as CNS trauma, ARDS, and severe pneumonia." (PMID 25076911, 2014). "Moreover, since the synthetic GHRH agonists have a longer serum half-life than the hypothalamic GHRH hormone itself, they can deliver a more potent signal for damaged lungs and provide the basis for novel treatment options for pneumonia and acute lung injury." (PMID 23860351, 2013).
triple-negative breast carcinoma (2 papers, 2012 to 2014). An invasive breast carcinoma which is negative for expression of estrogen receptor (ER), progesterone receptor (PR), and human epidermal growth factor receptor 2 (HER2). "We conclude that treatment of triple negative breast cancers with growth hormone-releasing hormone antagonists reduces tumor growth and potentiates the effects of cytotoxic therapy by nullifying drug resistance." (PMID 25593995, 2014). "This study evaluated the effects of a modern antagonistic analog of GHRH on tumor growth and on expression of inflammatory cytokine genes in two models of human triple negative breast cancers (TNBC)." (PMID 22941871, 2012). "This study evaluated the effects of an antagonistic analog of growth hormone-releasing hormone, MIA-602, on tumor growth, response to doxorubicin, expression of drug resistance genes, and efflux pump function in human triple negative breast cancers." (PMID 25593995, 2014).
type 1 diabetes (2 papers, 2024). "This underscores the significance of both hypothalamic and extrahypothalamic GHRH in type 1 diabetes." (PMID 39560873, 2024). "When MIA-602 was administered subcutaneously to the rats, impaired GLP-1 levels were restored, and dyslipidemia and hyperglucagonemia were blunted suggesting that antagonizing GHRH signalling in type 1 diabetes may improve GLP-1 function in the intestine." (PMID 39560873, 2024).
uveitis (2 papers, 2023). An inflammatory process affecting a part of or the entire uvea. "Consistent with data from GHRH-R deficient mice challenged with uveitis, GHRH antagonist protected mice from uveitis as well, while GHRH agonist promoted it." (PMID 37280225, 2023). "Clinical examinations by cSLO and OCT, and ocular histology showed that compared with the vehicle group (EAU + DMSO), mice treated with GHRH agonist (EAU + MR-409) developed more severe uveitis, while mice treated with GHRH antagonist (EAU + MIA-602) produced less uveitis." (PMID 37280225, 2023). "We have demonstrated that GHRH and GHRH-R were expressed in multiple ocular tissues, including the iris, ciliary body, retina, and eye-infiltrating leukocytes in the endotoxin-induced uveitis (EIU) animal model." (PMID 37280225, 2023). "Indeed, MIA-602, but not GHRH agonist MR-409, reduced the infiltration of macrophages and leucocytes and the production of TNF-α, IL-1β and MCP-1 in a preclinical model of LPS-induced uveitis." (PMID 37649486, 2023).
age (1 paper, 2013). A temporal measurement of the time period elapsed since an identifiable point in the life cycle of an organism. "A similar reversal of age-related memory deficits also occurs in response to peripheral administration of growth hormone or injection of growth hormone releasing hormone (GHRH) that increases both growth hormone and IGF-1 levels." (PMID 23847531, 2013).
anxiety disorder (1 paper, 2022). A category of psychiatric disorders which are characterized by anxious feelings or fear often accompanied by physical symptoms associated with anxiety. "The authors identified strong associations to individual disorders, such as GHRH with anxiety disorders, PREB with eating disorders, and GRIK5 with bipolar disorder." (PMID 35893041, 2022).
autism (1 paper, 2022). Persistent deficits in social interaction and communication and interaction as well as a markedly restricted repertoire of activity and interest as well as repetitive patterns of behavior. "However, we found that GHRH-KO mice lost preference for a stranger mouse, showing autism-related behavior." (PMID 36672612, 2022). "Our data indicate that expressions of BDNF, Grm3, Foxp1, Auts2 and Shanks3 in the hippocampus are significantly induced by L-serine administration in GHRH-KO mice via changed expression of epigenetic markers, which may ameliorate impairment of memory and autism-related behavior." (PMID 36672612, 2022).
autoimmune disease (1 paper, 2023). A disorder resulting from loss of function or tissue destruction of an organ or multiple organs, arising from humoral or cellular immune responses of the individual to their own tissue constituents. "Given the importance of GHRH signaling in Th17 differentiation and Th17 cell-mediated autoimmune ocular inflammation, we next addressed if this pathway also mediates other Th17 cell-driven autoimmune diseases." (PMID 37280225, 2023).
bladder cancer (1 paper, 2018). "In our preliminary studies on J82 bladder cancer, GHRH agonist MR-409 downregulated the expression of IGF1-R, inhibited the phosphorylation of IGF1-R and its downstream AKT and ERK pathways." (PMID 29983893, 2018).
brachydactyly (1 paper, 2016). A disease characterized by the presence of brachydactyly, including syndromic and non-syndromic forms. "Brachydactyly has been detected in half of the subjects with epigenetic alterations, in which the disease overts later in life, often with symptomatic hypocalcaemia, and also early TSH and GHRH resistances have been recorded." (PMID 27871293, 2016).
brain injury (1 paper, 2013). Acute and chronic (see also brain INJURIES, CHRONIC) injuries to the brain, including the cerebral hemispheres, CEREBELLUM, and brain STEM. "The use of GH-releasing peptide 6, which is an artificial hexapeptide activating the GHSR1a, in combination with GHRH, has been described as a potent GH-provocative test in several studies investigating pituitary dysfunction after traumatic brain injury." (PMID 24037787, 2013).
cardiomyopathies (1 paper, 2025). "Based on the compelling evidence for the role of GHRHR signaling in cardiac repair, GHRH/GHRH analogs are promising therapeutic candidates for multiple cardiomyopathies and further clinical translational research is needed." (PMID 39883351, 2025).
cognitive decline (1 paper, 2012). "In a different model of cognitive decline, the treatment of senescence accelerated mice (SAMP8) with another GHRH antagonist (MZ-5-156) also enhanced cognitive functions." (PMID 23211425, 2012).
colorectal cancer (1 paper, 2022). A primary or metastatic malignant neoplasm that affects the colon or rectum. "It has been previously reported that in lung, prostate and colorectal cancer, the additive growth‐inhibitory effects of growth hormone‐releasing hormone (GHRH) antagonists plus cisplatin in vitro and in vivo are most likely due to the suppression by antagonist of PI3K/Akt activity." (PMID 34866322, 2022).